BCL2 (BCL2 apoptosis regulator)
Diseases named in the same sentence as BCL2 in open-access papers (continued):
Sharing a sentence is not in itself a finding about the gene and the disease.
hematological malignancies (continued). "ABT-737 and its orally bioavailable analogue ABT-263 are potent, selective small-molecule inhibitors of Bcl-2 and Bcl-Xl, but not Mcl-1, showing potent clinical activity towards several hematological malignancies." (PMID 25008202, 2014). "This article reviews the latest clinical research progress on the use of BCL-2 inhibitors in different hematological malignancies and discusses the current status and future prospects of the combination of BCL-2 inhibitors with various new immunotherapies for hematological malignancies." (PMID 39060763, 2024). "This effective co-inhibition of BCL-2 and MCL-1 using BH3 mimetics was previously reported in hematological malignancies but not RMS." (PMID 35393436, 2022). "Furthermore, our data reveal that baseline expression of BCL‐2, BCL‐xL or MCL‐1 were not predictive of sensitivity to the BH3‐mimetics tested, similar to studies in hematological malignancies and solid tumors." (PMID 31228231, 2019).
hematological cancers (44 papers, 2015 to 2026). "The interaction between miR-15a-5p and BCL2 was first characterized in hematologic cancers, particularly chronic lymphocytic leukemia (CLL), where loss of miR-15a/16-1 leads to BCL2 overexpression and impaired apoptosis." (PMID 41561226, 2026). "ABT-199 (Venetoclax), a selective BCL-2 inhibitor, has demonstrated efficacy in treating BCL-2-dependent hematological cancers and is FDA-approved." (PMID 40141414, 2025). "Prolonged VEN therapy has been shown to reduce survival dependence of hematological cancers on Bcl-2, thereby promoting the selective survival of VEN-refractory cells." (PMID 40707672, 2025). "For example, BCL2, a key regulator of apoptosis, is frequently overexpressed in hematological tumors, contributing to chemotherapy resistance and poor prognosis." (PMID 41048997, 2025). "For the selection of targets, Bcl-2 was considered because it is widely used to obtain possible inhibitors used in the clinic in hematological cancers, including NHLs." (PMID 40565145, 2025). "This premise has led to continued research and the obtaining of potential Bcl-2 inhibitor molecules for the treatment of hematological cancers." (PMID 40565145, 2025). "While VEN triggers apoptosis in Bcl-2-dependent hematological cancers, other anti-apoptotic proteins such as Mcl-1 or Bcl-xL appear to play an important role(s) in VEN responsiveness." (PMID 40707672, 2025). "Our findings indicate that certain plasma proteins exhibit causative roles in various hematological tumors, specifically ISOC1 in 14 tumors, ADK in 11 tumors, FKBPL in 10 tumors, and BCL2 in 9 tumors." (PMID 41048997, 2025). "Pharmacological inhibition of these proteins, notably BCL2, has shown remarkable clinical efficacy and improved patient outcomes in several hematologic cancers." (PMID 38371625, 2024). "BCL2 protein primarily regulates the intrinsic apoptotic pathway, and BCL2 inhibitor (venetoclax) is widely used for treating hematological tumors." (PMID 39580422, 2024). "BCL-2 is an antiapoptotic protein commonly expressed in hematological cancers and plays an important role in their occurrence and development." (PMID 37894324, 2023). "Our review encompasses not only advancements in hematologic tumors but also a comprehensive overview of recent progress in employing BCL-2 inhibitors to treat solid tumors." (PMID 37894324, 2023). "This study has investigated the consequences of promoter SNPs in apoptosis genes Bax-248G>A (rs4645878)/Bcl-2-938C>A (rs2279115) and pro-inflammatory cytokines TNF-α rs1800629 G>A/IL-8 rs4073 T>A on the risk and susceptibility towards hematological cancers." (PMID 37232720, 2023). "MCL-1 has also emerged as an important resistance factor to BCL-2/BCL-XL specific BH3-mimetics in hematopoietic cancers, encouraging the investigation of combinatorial treatments to also target MCL-1." (PMID 35349392, 2022). "Venetoclax, a BCL-2 inhibitor used to treat certain hematological cancers, exhibits low oral bioavailability and high interpatient pharmacokinetic variability." (PMID 35456528, 2022). "Venetoclax induced apoptosis in hematological cancer cells dependent on Bcl-2 for their survival and tumor regression in preclinical xenograft models." (PMID 34073507, 2021). "Venetoclax, an FDA-approved BCL-2 inhibitor that is revolutionizing care in some BCL-2-expressing hematological cancers, affords an intriguing therapeutic possibility to treat SS." (PMID 34065859, 2021). "ABT-199 (Venetoclax) is a promising and selective inhibitor of Bcl-2 protein, which has exhibited clinical efficacy in multiple hematological cancers." (PMID 34638779, 2021). "Oxo-aglaiastatin inhibited translation in vitro and in vivo and synergized with doxorubicin, ABT-199 (a Bcl-2 antagonist), and dexamethasone when tested on hematological cancer cells." (PMID 30718665, 2019).
hematological cancers (continued). "For instance, venetoclax (ABT-199/GDC-0199) is typical Bcl-2 inhibitor that plays a role as BH3 mimic for the treatment of Bcl-2-dependent hematological cancers." (PMID 32257914, 2019). "For example, it has been indicated that hematopoietic cancers are dependent upon Bcl-2 for survival or resistance to stress, whereas epithelial cancers rely on Bcl-xL for chemoresistance." (PMID 27579319, 2016). "These available reports suggest that hematological cancer cell survival is Bcl-2-dependent, whereas solid cancers typically depend more on Mcl-1 for their survival." (PMID 26009874, 2015). "We recently described the BCL-2-selective inhibitor venetoclax to show superior potency to navitoclax in pre-clinical models of hematological cancers." (PMID 26565405, 2015). "Indeed, venetoclax has achieved FDA approval and has revolutionized treatment for hematological cancers that are reliant on BCL-2." (PMID 37685889, 2023). "Indeed, venetoclax (ABT-199), an FDA-approved BCL-2-specific inhibitor, does just this, and has revolutionized treatment for hematologic cancers." (PMID 37685889, 2023). "Despite significant advances in the treatment of hematologic cancers with BTK inhibitors (e.g., ibrutinib) and BCL-2 inhibitors (e.g., venetoclax), resistance and disease relapse remain major challenges." (PMID 41479906, 2025). "Due to the important function of Bcl-2 in B-cells, clinical studies with ABT-199 presently concentrate exclusively on hematological cancers." (PMID 34638779, 2021). "It is evident that Bcl-2 inhibitors do not seem to be as efficient against solid tumors as they are against hematological cancers, when used as single agents." (PMID 36639602, 2023). "Importantly, combinatorial targeting of BCL-2 and MCL-1 is tolerated in mice and is under investigation in clinical trials of hematological cancers (NCT03672695, NCT04702425)." (PMID 35349392, 2022). "In the same study, 2-DG rapidly affected steady-state MCL-1 levels, sensitizing human hematopoietic tumor cell lines to ABT-737, a nonselective BCL-2/BCL-XL-antagonizing BH3 mimetic." (PMID 37684238, 2023). "As a BCL-2 inhibitor with high oral bioavailability and high specificity for BCL-2, venetoclax is able to markedly inhibit the survival of BCL-2-dependent hematological tumors without affecting platelets, providing high hopes for clinical practicability." (PMID 37894324, 2023).
adenocarcinoma (36 papers, 1996 to 2025). A common cancer characterized by the presence of malignant glandular cells. "In GC, Bcl-2 is overexpressed, especially in H. pylori- associated adenocarcinoma, however, while several studies have assessed the relationship between Bcl-2 expression and prognosis in GC, results have been inconsistent." (PMID 32117120, 2020). "Polymorphous adenocarcinoma is another cause of diagnostic pitfall; however compared to the alveolar variant of ILC, it is triple-negative, BCL-2 positive, and E-cadherin-positive, and often has an aggressive course in young patients." (PMID 39099959, 2024). "Our findings reveal that this synergistic treatment not only significantly reduces prostate weight and mitigates adenocarcinoma proliferation but also attenuates anti-apoptotic BCL-2 protein expression." (PMID 38671015, 2024). "There was an inverse correlation of mononuclear stromal reaction and bcl-2 expression in adenocarcinoma (p < 0.0005)." (PMID 36766867, 2023). "Immunoreactivity for bcl-2 was observed in 41.4% of NSCLCs, 51% of squamous and 34.8% of adenocarcinomas-expressed Bcl-2." (PMID 36766867, 2023). "According to data analyzed, overexpression of LC3 (P=0.0171) was detected in adenocarcinoma subtype compared to SCC subtype, although the overexpression of bcl2 in adenocarcinoma compared with SCC subtype was less consistent (P= 0.446)." (PMID 33773561, 2021). "They observed that the expression levels of Bcl-2 and bcl-xl in the adenocarcinoma cell line increased with CXCL12 therapy and decreased with CXCR4 antagonist and JAK2 inhibitor therapy." (PMID 31718601, 2019). "In this study, chemically-induced adenocarcinomas in rats were resistant to proapototic changes and signaling (caspase-3, Bax/Bcl-2) which were observed in MCF-7 and MDA-MB-231 cells after herbal treatment." (PMID 30970626, 2019). "In adenocarcinoma A549 cells, DN induced G2/M-phase cell cycle arrest and apoptosis, at least in part, via mitochondrial membrane permeabilization mediated by Bax and Bcl-2 proteins, leading to caspase-3 activation." (PMID 25342427, 2014). "Expressão prognóstica da proteína bcl-2, por técnica imunohistoquímica em portadores de adenocarcinoma da próstata submetidos a prostatectomia radical." (PMID 11500787, 2001). "O aumento na expressão da proteína bcl-2 em tumores de próstata com escore de Gleason elevado pode estar associado à progressão do adenocarcinoma de próstata." (PMID 11500787, 2001). "According to this study, BCL2 expression could be useful as a marker and a predictor of neoadjuvant chemotherapy for adenocarcinomas." (PMID 40361484, 2025). "Finally, Birinapant and AT-406 can synergise with BCL-2 inhibitor ABT-199 to reduce viability of adenocarcinoma cells with high BCL-2 expression." (PMID 27520705, 2016). "Notably, high levels of BCL-2 protein are detected in RKO adenocarcinoma cell line." (PMID 27520705, 2016). "When cells are engineered to over-express MYC, BCL2 and activated AKT (ACB genes, for AKT, c-MYC and BCL2), they transform to adenocarcinoma." (PMID 39858043, 2025). "We examined the expression of several proteins involved in proliferation (PCNA), apoptosis (PARP, caspase-3, BAX, BCL-2, and BCL-XL and mammary carcinogenesis (ERα and HER2) in carefully selected representative sentinel adenocarcinomas from each diet group." (PMID 24465421, 2014). "Additionally, we observed an inverse correlation in the expression of Bcl-2 and VEGF in NSCLC and mononuclear reaction and bcl-2 expression in adenocarcinomas." (PMID 36766867, 2023). "Additionally, we observed a inversely correlation in the expression of Bcl-2 and VEGF in NSCLC patients and inverse correlation of mononuclear stromal reaction and bcl-2 expression in adenocarcinomas." (PMID 36766867, 2023). "Tumors in WT mice were predominately adenocarcinomas with NF-κB activation, while bcl-3−/− lesions were largely squamous lacking NF-κB and with low Bcl-2 expression." (PMID 35681213, 2022).
adenocarcinoma (continued). "Cells of the adenocarcinoma component were CAM.5.2, CK7, CK AE1/AE3, and GATA-3 positive and negative for synaptophysin, chromogranin A, parathormone, parafibromin, thyroglobulin, TTF1, calcitonin, glucagon, S100, PGP-9 and Bcl-2." (PMID 32506375, 2021). "Bcl-2 immunopositivity is more common in low-grade, early-stage adenocarcinomas rather than in high-grade, advanced-stage adenocarcinomas, but the difference was not statistically significant." (PMID 24314145, 2013). "Importantly, there were 4 other BCL2-positive tumors, without neuroendocrine marker expression, which were identified as adenocarcinomas." (PMID 39286979, 2024). "Furthermore, in human adenocarcinoma MCF-7 cells, TQ induced apoptosis, by disrupting mitochondrial membrane potential and activating caspases and PARP cleavage and increasing Bax/Bcl2 ratio, arrested cell cycle at G2/M and sub-G1 phase via the modulation of the Akt/PTEN axis." (PMID 33916916, 2021).
neurodegenerative disease (30 papers, 2013 to 2025). A disorder of the central nervous system characterized by gradual and progressive loss of neural tissue and neurologic function. "The results revealed that compared with the control group, the apoptotic proteins p-CSF-1R/CSF-1R, p-Nrf2/Nrf2, and Bcl-2/Bax, associated with neuronal injury and degenerative diseases, were significantly decreased, and cleaved caspase-3 expression was significantly increased." (PMID 40278547, 2025). "Therefore, Bcl-2 may be a crucial target for study of the mechanisms underlying abnormal autophagy observed in these neurodegenerative diseases." (PMID 23658815, 2013). "Previous studies have demonstrated that dysregulated metabolism of DNA epigenetic modifications leads to the regulation of neuronal apoptosis-related gene expression, including BAX and Bcl-2, in the pathogenesis of neurodegenerative disease." (PMID 40386213, 2025). "BCL2 upregulation has been unexpectedly detected in response to hypoxia, ischemia, and neurodegenerative diseases and was explained as a compensatory mechanism preventing neurons from acute or chronic injury." (PMID 38064105, 2024). "The correlation analysis showed that Nurr1 was positively correlated with Bcl2 in the amygdala and nucleus accumbens, which were closely related to neurodegenerative diseases." (PMID 36419251, 2023). "Evidence indicates that Bcl-2 and Bax are involved in mitochondria-mediated apoptosis in neurodegenerative diseases." (PMID 31549045, 2019). "This concluded that JNK/NF-κB/TNF-α-mediated cross-talk in the activated microglia is the major underlying reason for neuronal death through the activation of the Bcl-2 gene family in various neurodegenerative diseases." (PMID 28671636, 2017). "The anti-apoptotic protein Bcl-2 plays a pivotal role in regulating neuronal apoptosis under many adverse conditions such as neurodegenerative diseases, ischemia, oxidative stress and trauma." (PMID 27768775, 2016). "Moreover, the protective effect of vitagens against oxidative stress-induced neurodegenerative diseases was attributed to the inhibition of neuronal apoptosis subsequent to the upregulation of HO-1 and Bcl2 levels." (PMID 37368180, 2023). "In addition, BCl-2 is considered a tissue homeostasis indicator in vascular, heart, and neurodegenerative diseases." (PMID 35893792, 2022). "Several studies have indicated that upregulation of Bax and downregulation of Bcl-2 trigger cytochrome c release from the mitochondria into the cytosol, leading to apoptosis and eventually may contribute to the pathogenesis of neurodegenerative diseases." (PMID 33551748, 2020). "In addition, EGCG was found to modulate expression of proapoptotic genes like Bax, Bad, and Mdm2 whilst genistein induced changes in the expression of the Bcl-2 gene, thereby increasing survival of cells in neurodegenerative diseases." (PMID 26576219, 2015).
blood cancers (29 papers, 2016 to 2025). "Dysregulated BCL-2 signaling is a hallmark of many hematological neoplasms, including B-ALL." (PMID 35778418, 2022). "The BCL2 inhibitor venetoclax is currently being evaluated in Phase I trials that include both pediatric blood cancers and NB (NCT03236857)." (PMID 40854877, 2025). "Although BCL-2 inhibitors have been widely studied for their groundbreaking effects in the treatment of hematological neoplasms, little is known about targeting BCL-2 for regulating chemokines during the antitumor immune response." (PMID 38062129, 2024). "Although the resistance factor BCLxL-BAK complex also decreased for BC-7064-R, the weakened BCL2 dependence led to an estimated score of 0.36, explaining the relapse of this specific blood cancer." (PMID 39025942, 2024). "Researchers successfully developed ABT-199 (Venetoclax) with super Bcl-2 selectivity that exhibited efficacy in hematologic tumor but spared platelets." (PMID 39372954, 2024). "Its extract MTE also exerts a potent potential of inducing apoptosis through upregulating proapoptotic Bax, caspase‐9, and caspase‐3 and downregulating cyclin D1 and antiapoptotic Bcl‐2 in hematologic neoplasm cells." (PMID 36756719, 2023). "Using genetic and pharmacological tools across multiple cell line models of blood cancer, we demonstrated that selective BCL2 inhibitors have important flow-on effects that includes the redistribution of BH3-only proteins to ancillary pro-survival proteins not directly engaged by the inhibitor." (PMID 40204951, 2025). "As autophagy seems to play an important role in this aggressive blood cancer, it would be interesting to test/develop therapeutics to target this process, for instance nano-targeting and/or modulation of key autophagy and apoptosis components (such as beclin-1 and Bcl-2) in M1 macrophages." (PMID 41415285, 2025). "The Bcl-2 gene has been demonstrated to be highly expressed in blood cancers, and the level of Bcl-2 expression has been found to be elevated in the accelerated/blastic phase of CML cells compared to the chronic stage which might drive the progression to the advanced stages." (PMID 37232720, 2023). "The selective BCL-2 inhibitor venetoclax (VEN; ABT-199) demonstrated efficacy both preclinically and clinically in a broad range of hematologic neoplasms and is currently being evaluated for its clinical implication in ALL." (PMID 36674872, 2023). "Agents worth testing in combination studies include FLT3 inhibitors in AML, BCR signaling inhibitors in certain NHL subtypes, and BH3 mimetic drugs (BCL2 inhibitor venetoclax and MCL-1 inhibitors) in a variety of blood cancers." (PMID 34408976, 2021). "We and others have demonstrated that Mcl-1 plays an important role in the antileukemic activity of the Bcl-2-selective inhibitor ABT-199 in AML and other blood cancer cells." (PMID 27166183, 2016). "For example, it is not fully understood why BCl-2 inhibitors or proteasome inhibitors are not effective in most types of blood cancer." (PMID 41226551, 2025). "Bcl-2 inhibition only affected the survival of hematological tumor cells, but not on solid tumor cells." (PMID 39372954, 2024). "The BCL-2 inhibitor venetoclax (VEN) has proven great clinical value in other blood cancers, however, data on B-ALL is sparse and past studies have not so far described the effects of VEN on gene and protein expression profiles." (PMID 35778418, 2022).